TGFBI (transforming growth factor beta induced)
Description:
Plays a role in cell adhesion. May play a role in cell-collagen interactions (By similarity).
Synonyms: BIGH3; CDB1; CDGG1; CDG2; CSD; CSD1; CSD2; CSD3; EBMD; LCD1
Tractability: Antibody: UniProt places it where antibodies can reach, with high confidence; its Gene Ontology location is reachable by antibodies, with high confidence; UniProt predicts a signal peptide or a membrane-spanning region. PROTAC: ubiquitination databases record sites on it; its protein half-life has been measured.
Target class: Adhesion
Gene: Protein-coding gene on chromosome 5 (136,028,988 to 136,063,818, forward strand). Ensembl gene ENSG00000120708.
Subcellular location: Secreted; Secreted, extracellular space, extracellular matrix
Pathways (Reactome):
Metabolism of proteins: Amyloid fiber formation
Gene Ontology:
Molecular function: collagen binding; identical protein binding; protein binding; cell adhesion molecule binding; extracellular matrix structural constituent; integrin binding; extracellular matrix binding
Biological process: angiogenesis; cell population proliferation; extracellular matrix organization; homophilic cell-cell adhesion; negative regulation of cell adhesion; visual perception; chondrocyte differentiation
Cellular component: extracellular exosome; extracellular matrix; extracellular region; trans-Golgi network; elastic fiber; non-collagenous component of interstitial matrix; plasma membrane; basement membrane; microfibril
Genetic constraint (gnomAD): Loss-of-function variants: 50 observed, 73.95 expected, observed/expected ratio (o/e) 0.68, 90% interval 0.54 to 0.86. The upper end of that interval is the gene's LOEUF score, 0.86, which puts it in group 3 of 6, group 1 being the genes least tolerant of losing a copy. Missense variants: 839 observed, 887.13 expected, observed/expected ratio (o/e) 0.95, 90% interval 0.89 to 1. Synonymous variants: 362 observed, 362.7 expected, observed/expected ratio (o/e) 1, 90% interval 0.92 to 1.09.
Homologues: Orthologues: chimpanzee TGFBI (99% identical), dog TGFBI (93% identical), guinea pig TGFBI (91% identical), mouse Tgfbi (91% identical), rat Tgfbi (90% identical), macaque TGFBI (89% identical), pig TGFBI (89% identical), rabbit TGFBI (86% identical), tropical clawed frog tgfbi (72% identical), zebrafish tgfbi (61% identical), Drosophila melanogaster Fas1 (19% identical), Caenorhabditis elegans F26E4.7 (19% identical). Paralogues in human: POSTN (44% identical).
Diseases named in the same sentence as TGFBI in open-access papers:
TGFBI is named in the same sentence as 225 diseases in open-access papers, as found by Europe PMC text mining. Sharing a sentence is not in itself a finding about the gene and the disease. The quoted sentences say what the papers report.
corneal dystrophies (97 papers, 2007 to 2026). "Over 70 mutations in the transforming growth factor beta-induced (TGFBI) gene are associated with corneal dystrophies that impair vision." (PMID 41828635, 2026). "In the cornea, ex vivo studies have shown that CRISPR/Cas9 can precisely correct pathogenic TGFBI mutations in patient-derived keratocytes, supporting the concept of mutation-specific gene editing for monogenic corneal dystrophies." (PMID 41595486, 2026). "The first reported pathological manifestation related to TGFBI was corneal dystrophies due to its mutations." (PMID 38395907, 2024). "We found that variants of the TGFBI gene caused many corneal dystrophies, and the genotype correlated strongly with the phenotype." (PMID 39271608, 2024). "For instance, an established corneal dystrophy variant in TGFBI, NM_000358.3: c.1664G > A; p.(Arg555Gln), has predictions of benign or uncertain classification in several in-silico predictors, SIFT = 0.267, EVE = 0.1704, and REVEL = 0.567 (dbNSFP version 4.8)." (PMID 39169229, 2024). "Age-dependent progressive accumulation of mutant TGFBI protein (TGFBIp) in the corneal stroma is the hallmark of TGFBI-linked corneal dystrophy, including GCD2, and interferes with corneal transparency." (PMID 36980838, 2023). "Mutated TGFBI protein appears to specifically accumulate in the cornea versus other tissues in patients with TGFBI-associated corneal dystrophies." (PMID 37239394, 2023). "A wide assortment of corneal dystrophies were found to be associated with TGFBI (transforming growth factor beta induced) mutations." (PMID 37138096, 2023). "We are unaware of a previous report of corneal dystrophy associated with thep.(Ser591Phe) variant in TGFBI." (PMID 33645289, 2022). "In early studies, the research of TGFBI mainly focused on corneal dystrophy as it is a primary disease-causing gene of corneal dystrophy, leading to protein deposits on the cornea then cause blindness." (PMID 36398072, 2022). "Previous studies have suggested that a strong correlation between phenotypic change and genotypic mutations for the majority of TGFBI corneal dystrophies including GCD and LCD." (PMID 33513810, 2021). "We enrolled siblings aged 15 and 17 years who had one-year-old brothers with corneal dystrophy and concomitant retinal pigmentary degeneration and found a TGFBI mutation." (PMID 33946315, 2021). "To date, 74 mutations in the transforming growth factor-β–induced (TGFBI) gene have been associated with the group of rare autosomal dominant diseases, TGFBI-linked corneal dystrophies (CDs)." (PMID 34097874, 2021). "This means that CHST6 has mutation diversity, which clearly distinguishes it from the hot-spot mutations of transforming growth factor beta-induced (TGFBI) corneal dystrophy." (PMID 34645431, 2021). "The transforming growth factor beta-induced (TGFBI) gene has been implicated in the pathogenesis of KC and a heterogeneous group of corneal dystrophies that are characterized by the progressive loss of corneal transparency." (PMID 34746916, 2021). "This study contributes to the understanding of the molecular mechanisms involved in protein aggregation in GCD1 and GCD2, some of the most frequent TGFBI-linked corneal dystrophies." (PMID 34097874, 2021). "Regarding the distribution of TGFBI mutations in each phenotype of corneal dystrophy, patients with GCD1 consisted of 3 patients with R124H and 8 patients with R555W, and those with GCD2 comprised 5 patients with R124H and 1 patient with R124C." (PMID 33513810, 2021). "There is a category of seven corneal dystrophies, epithelial-stromal TGFBI dystrophies, that are all caused by 70 reported mutations in TGFBI42–44." (PMID 34381080, 2021). "TGFBI-associated corneal dystrophies are protein aggregation disorders in which the mutant TGFBIp aggregates and accumulates in the cornea, leading to a reduction in visual acuity and blindness in severe cases." (PMID 32132634, 2020).
corneal dystrophies (continued). "Granular corneal dystrophy type 2 (GCD2) is the most common form of transforming growth factor β‐induced (TGFBI) gene‐linked corneal dystrophy and is pathologically characterized by the corneal deposition of mutant‐TGFBIp." (PMID 32667742, 2020). "Mutations in transforming growth factor-beta-induced (TGFBI) gene cause clinically distinct types of corneal dystrophies." (PMID 32029872, 2020). "Stromal corneal dystrophies associated with mutations in the Transforming Growth Factor-Beta Induced (TGFBI) gene, located on chromosome 5q315–8 are inherited protein aggregation disorders." (PMID 32132634, 2020). "TGFBI corneal dystrophies are caused by a point mutation, or insertion or deletion of some frames, in TGFBI, which is located on chromosome 5q311,2." (PMID 32029872, 2020). "The formation of insoluble amyloid aggregates is a pathological hallmark of TGFBI-associated corneal dystrophies." (PMID 32132634, 2020). "To understand the effect of TGFBI mutation in corneal dystrophy, we generated mutant mice with the Tgfbi R124C mutation, which is the representative mutation causing LCD1, using the CRISPR/Cas9 approach." (PMID 32029872, 2020). "A similar approach showed successful disruption of TGFBI (transforming growth factor–β-induced) mutant alleles relevant for corneal dystrophies; however, cleavage of the wild-type copy was also observed." (PMID 32823625, 2020). "TGFBI variants have been frequently identified in patients with corneal dystrophies, as well as KTCN." (PMID 32879808, 2020). "Different TGFBI mutations can cause specific corneal dystrophies, and a genotype-phenotype correlation has been demonstrated at two mutation hotspots, R124 and R555." (PMID 30760895, 2019). "Due to significant genetic heterogeneity, the clinical phenotypes of TGFBI-linked corneal dystrophy vary." (PMID 30805211, 2019). "Approximately 12 pathogenic genes have been linked to corneal dystrophy, among which the human transforming growth factor beta-induced (TGFBI) gene (encoding an extracellular matrix adhesion protein) is most commonly linked." (PMID 30805211, 2019). "It has been confirmed that the following types of corneal dystrophies are caused by TGFBI gene mutations: granular corneal dystrophy (GCD), Avellino corneal dystrophy (ACD), Reis–Bücklers corneal dystrophy (RBCD), and lattice corneal dystrophy (LCD)." (PMID 30805211, 2019). "The purpose of the present study was to explore the potential application of TGFBI gene mutation identification in the classification and diagnosis of corneal dystrophy." (PMID 30805211, 2019). "A commercially available genetic test has been developed that can detect within the TGFBI gene the five most common mutations which are linked to the five more common types of corneal dystrophy." (PMID 30760895, 2019). "There is a high degree of correlation between the phenotypes and genotypes of TGFBI-linked corneal dystrophies." (PMID 30805211, 2019). "It has been confirmed that specific types of TGFBI gene mutations are highly correlated with specific clinical phenotypes of corneal dystrophy." (PMID 30805211, 2019). "Although only four cases of TGFBI corneal dystrophy associated with M502V have been reported within the literature, we discovered a heterozygous mutation for M502V in one sample." (PMID 30760895, 2019). "TGFBI-associated corneal dystrophies exhibit multiple clinical phenotypes and a high degree of genetic heterogeneity." (PMID 30805211, 2019). "Corneal dystrophy is an autosomal dominant disorder caused by mutations of the transforming growth factor β-induced (TGFBI) gene on chromosome 5q31.8." (PMID 30753226, 2019). "Genetic information is an important factor in diagnosis of corneal dystrophy, and it is now acknowledged that different mutation types of TGFBI gene can lead to different corneal dystrophy subtypes." (PMID 31438893, 2019).
corneal dystrophies (continued). "In this study, the role of HtrA1 in the pathophysiology of TGFBI-linked corneal dystrophy was investigated by examining the ability of HtrA1 to cleave WT TGFBIp and seven mutants as well as WT FAS1-4 and six mutants." (PMID 31197037, 2019). "Corneal dystrophies caused by mutation of TGFBI gene was common in superficial cornea, making PTK an appropriate surgical treatment." (PMID 31438893, 2019). "The advent of genetic analysis has allowed the identification of transforming growth factor β-induced gene (TGFBI) mutations that are associated with specific corneal dystrophies." (PMID 30753226, 2019). "Specifically, we predict that autologous transplantation of LESCs containing either a TGFBI gene knockout or a corrected TGFBI allele represents a feasible treatment strategy for corneal dystrophy patients." (PMID 30753226, 2019). "This five-mutation genetic test was originally designed for the Korean and Japanese population, where a majority of the TGFBI corneal dystrophy cases are diagnosed as GCD2 caused by the R124H mutation." (PMID 30760895, 2019). "China was distinct from other Asian countries in that the GCD1 mutation was most frequently identified in TGFBI corneal dystrophy patients, followed by the LCD1 and GCD2 mutations." (PMID 30753226, 2019). "In the case of TGFBI corneal dystrophies, of the 60 causative mutations less than a third generate a novel S. pyogenes PAM." (PMID 29170458, 2017). "TGFBI is a primary disease-causing gene associated with corneal dystrophy where mutations cause protein deposits on the cornea eventually leading to blindness." (PMID 28750100, 2017). "Characterization of TGFBI in disease has primarily focused on corneal dystrophy where human mutations in the gene encoding this protein cause aberrant folding leading to TGFBI aggregation in the cornea resulting in blindness." (PMID 28750100, 2017). "An allele-specific approach to target the five most prevalent TGFBI corneal dystrophy mutations is investigated, which highlights the promiscuity of Cas9 and the need for a validated, highly specific approach, that will encompass all possible TGFBI mutations." (PMID 29170458, 2017). "Recent studies have shown the accumulation of different proteolytic fragments of TGFBIp with diverse cleavage sites in the amyloid deposits of patients with TGFBI-linked corneal dystrophy." (PMID 25853243, 2015). "Age-dependent TGFBIp accumulation and deposition has been observed in the corneal stroma of patients with TGFBI-linked corneal dystrophy." (PMID 25853243, 2015). "Current therapeutic strategies for the treatment of TGFBI-linked corneal dystrophy are focused on inhibiting TGFBIp expression by blocking the TGF-β signaling pathway." (PMID 25853243, 2015). "The findings of this study will enable the identification of therapeutic targets for the treatment of TGFBI-linked corneal dystrophy." (PMID 25853243, 2015). "Specifically, we investigated the intracellular and extracellular trafficking of TGFBIp and its involvement in the pathogenesis of TGFBI-linked corneal dystrophy." (PMID 25853243, 2015). "Progressive accumulation of mutant TGFBIp is directly involved in the pathogenesis of TGFBI-linked corneal dystrophy." (PMID 25853243, 2015). "Despite the demonstration of the role of TGFBIp accumulation in the pathogenesis of TGFBI-linked corneal dystrophy, the molecular mechanisms involved in extra- and intracellular trafficking of TGFBIp are poorly understood." (PMID 25853243, 2015). "In conclusion, a good phenotype–genotype correlation was observed in most patients with TGFBI-linked corneal dystrophies." (PMID 22355247, 2012). "A wide range of variant stromal/Bowman’s layer corneal dystrophies has been found to be associated with different TGFBI mutations." (PMID 22355247, 2012). "Mutations in the TGFBI gene are well characterized in a number of corneal dystrophies, which lead to the development of corneal deposits and impaired vision." (PMID 22949874, 2012).
corneal dystrophies (continued). "In this first comprehensive report of TGFBI mutations in a Korean population, we detected three corneal dystrophy types (TBCD, GCD2, and LCD)." (PMID 22876129, 2012). "Clinical phenotypes and genotypes of the probands of 15 families with TGFBI-linked corneal dystrophies." (PMID 22355247, 2012). "In conclusion, we report here phenotype-genotype correlations and novel mutations in a Korean population with TGFBI-related corneal dystrophies." (PMID 22876129, 2012). "In most cases, TGFBI-linked corneal dystrophies had good phenotype–genotype correlations; however, some phenotypic variation was present." (PMID 22355247, 2012). "In this study, we aimed to identify the clinical features and genetic mutation spectrum in patients with TGFBI-linked corneal dystrophies from the National Taiwan University Hospital, Taipei, a tertiary-care referral medical center in northern Taiwan." (PMID 22355247, 2012). "Corneal dystrophy–related mutations are more likely to disrupt the interaction of TGFBI with critical binding proteins than affect the whole protein structure." (PMID 22605926, 2012). "Transforming growth factor-beta induced (TGFBI)-related corneal dystrophies arise from heterozygous mutations in the transforming growth factor-beta induced gene (TGFBI), which is located on human chromosome 5q31." (PMID 22605926, 2012). "Investigation of the influence of TGFBI mutations on cell ER stress would help to characterize the mechanisms underlying TGFBI-related corneal dystrophy." (PMID 22605926, 2012). "Five distinct TGFBI mutations were identified in these 15 families having different subtypes of corneal dystrophies." (PMID 22355247, 2012). "To gain insight into the mechanism underlying TGFBI-related corneal dystrophies, we first investigated the influence of the Arg555Trp and Thr538Pro TGFBI mutant proteins on C-terminal cleavage and ER stress." (PMID 22605926, 2012). "We identified five distinct mutations responsible for TGFBI corneal dystrophies (p.R555Q, p.R124H, p.R124C, p.L527R, and p.P542R)." (PMID 22876129, 2012). "We identified five distinct mutations responsible for TGFBI corneal dystrophies (R124R, R124H, R555W, R555Q, and H626R)." (PMID 21921985, 2011). "Researchers have established that TGFBI corneal dystrophies are inherited with complete penetrance and dominance and certain TGFBI mutations are correlated with a specific phenotype." (PMID 21921985, 2011). "In conclusion, this study underlines the role of comprehensive phenotype-genotype analysis in TGFBI corneal dystrophies, describes the TGFBI mutation spectrum in a Polish population and reveals the phenotypic heterogeneity in the case of the H626R mutation." (PMID 21921985, 2011). "This study underlines the role of comprehensive phenotype-genotype analysis in TGFBI corneal dystrophies, describes for the first time the TGFBI mutation spectrum in a Polish population and reveals phenotypic heterogeneity in the case of the H626R mutation." (PMID 21921985, 2011). "Since 1994 three types of autosomal dominant corneal dystrophies and TGFBI were mapped to chromosome 5 (5q31), more than 30 mutations in TGFBI have been identified to be associated with corneal dystrophies with distinct subtypes being confirmed." (PMID 21311742, 2011). "In Family C, we have identified a complex TGFBI allele [p.Met502Val;p.Arg555Gln] associated with a corneal dystrophy of an unspecified type." (PMID 21617751, 2011). "Other types of corneal dystrophies arise from mutations in the transforming growth factor beta-induced gene (TGFBI, also known as BIGH3) on chromosome 5q31." (PMID 22174841, 2011). "Numerous studies have indicated that TGFBI is the important disease gene underlying corneal dystrophy." (PMID 22194646, 2011). "This underlines the need for precise phenotype analysis and TGFBI screening for definite diagnosis and classification of corneal dystrophies." (PMID 21921985, 2011).